ANKRD63 (ankyrin repeat domain 63)
Tractability: No criterion of Open Targets' tractability assessment is met for any kind of drug.
Gene: Protein-coding gene on chromosome 15 (40,278,372 to 40,283,064, reverse strand). Ensembl gene ENSG00000230778.
Subcellular location (Human Protein Atlas): Mitochondria
Genetic constraint (gnomAD): Loss-of-function variants: 17 observed, 13.09 expected, observed/expected ratio (o/e) 1.3, 90% interval 0.88 to 1.84. The synonymous counts are far from expectation, so gnomAD's model fits this gene poorly and the ratio says little. Missense variants: 513 observed, 451.15 expected, observed/expected ratio (o/e) 1.14, 90% interval 1.06 to 1.22. Synonymous variants: 315 observed, 226.24 expected, observed/expected ratio (o/e) 1.39, 90% interval 1.27 to 1.53.
Homologues: Orthologues: chimpanzee ANKRD63 (99% identical), macaque ANKRD63 (98% identical), dog ANKRD63 (96% identical), pig ANKRD63 (94% identical), mouse Ankrd63 (92% identical), rat Ankrd63 (92% identical), guinea pig ANKRD63 (79% identical), tropical clawed frog ANKRD63 (33% identical). Paralogues in human: TANC1 (21% identical), TANC2 (21% identical), CTTNBP2 (19% identical), ANKRD65 (14% identical).